CYP3A4 (cytochrome P450 family 3 subfamily A member 4)
Diseases named in the same sentence as CYP3A4 in open-access papers (continued):
Sharing a sentence is not in itself a finding about the gene and the disease.
COVID-19 (continued). "Therefore, it is also plausible that repurposed medications metabolized by CYP3A4 may present sexual dimorphism in pharmacokinetic, which could also be due to the major inflammation observed in men with COVID-19 than in women." (PMID 34451827, 2021). "Our study is the first comprehensive in-silico analysis of CYP3A4/5 missense SNPs and their effects on the enzyme-drug interactions of FDA/EMA-licensed COVID-19 antiviral drugs." (PMID 39819897, 2025). "Hence, we believe the findings reported in this study may improve our understanding of the CYP3A4 protein binding landscape, which in turn could pave the way for an understanding of the use of ivermectin as an alternative treatment for COVID-19 by individuals with diabetes and/or hypertension." (PMID 39596155, 2024). "Using network pharmacology, we identified 7 core targets of curcumol against COVID-19 and COAD, including GABRD, GABRP, BCHE, CYP3A4, PGR, HSD17B2, and SLC6A3." (PMID 35967794, 2022). "The present study explores the effect of Ashwagandha and AYUSH-64 on important human CYP enzymes (CYP3A4, CYP2C8, and CYP2D6) to assess their interaction with remdesivir, a drug used for COVID-19 management during the second wave." (PMID 36313313, 2022). "Notably, CYP3A4 and ENT2 were strongly localized in lymphocytes in COVID-19 compared to control human lung tissues." (PMID 37180730, 2023). "Accumulating evidences have showed that PK DDIs, primarily related to the presence of CYP3A4, might contribute to DILI in COVID-19 patients." (PMID 35979235, 2022).
prostate carcinoma (40 papers, 2003 to 2026). A carcinoma that arises from epithelial cells of the prostate gland. "Several additional studies about CYP3A4*1B on prostate cancer susceptibility would greatly improve the power of the present meta-analysis on this polymorphism." (PMID 41514571, 2025). "The aim of the present study is to investigate the ethnicity-related clinical impact of CYP3A4 variants on prostate cancer risk." (PMID 41514571, 2025). "Further experimental data from genetic association studies are necessary to clarify the relationship between CYP3A4*1B (rs2740574, −392 A > G) polymorphism and prostate cancer susceptibility in European Caucasians." (PMID 41514571, 2025). "For example, a study on multidrug resistance-associated proteins demonstrated that CYP3A4 overexpression would lead to the acquisition of doxorubicin resistance in human prostate cancer LNCaP, osteosarcoma MG-63, and chondrosarcoma SW-1353 cells." (PMID 40630116, 2025). "In conclusion, our results indicate a potential association between CYP3A4*1B and prostate cancer predisposition, suggesting a role in the relationships of different genotypes in disease susceptibility." (PMID 41514571, 2025). "In the present systematic review and meta-analysis, we aimed to assess and highlight the most important polymorphic pharmacogenetic markers of the CYP3A4 gene associated with prostatic neoplasia, particularly with prostate cancer risk in European Caucasians." (PMID 41514571, 2025). "The study aimed to assess the impact of CYP3A4*1B polymorphism on prostate cancer risk in populations of European Caucasian ancestry." (PMID 41514571, 2025). "In particular, the reduced expression of CYP3A4 is associated with prostate cancer development and has an inverse correlation with Gleason score and patient prognosis." (PMID 41514571, 2025). "Published data on the association between CYP3A4 A392G and the risk of prostate cancer remains controversial." (PMID 41514571, 2025). "We evaluated the association between the CYP3A4*1B (rs2740574, −392 A > G) variant and prostate cancer risk in European Caucasians." (PMID 41514571, 2025). "The risk of prostate cancer increased with the increased frequency of allele variants of the prostate cancer gene CYP3A4 and SRD5A2, which was found in higher frequencies among Africans, particularly Senegalese and Ghanaians, than other races." (PMID 40313245, 2025). "The selection of CYP3A4*1B polymorphism was correct because testosterone, which is associated with prostate cancer, is metabolized by CYP3A4 cytochrome." (PMID 31025537, 2019). "In agreement with previous studies, the present data suggest that the CYP3A4*1B polymorphism appears to be a gene with low penetrance and therefore has moderate effects on the risk of developing prostate cancer." (PMID 24924803, 2014). "Twenty five percent of the prostate cancer patients with a TNM≥3 were heterozygous for the CYP3A4 variant and had an OR of 3.16 compared to the *1A/*1A genotype, but this difference was not statistically significant (p = 0.10)." (PMID 24924803, 2014). "Levels of enzymes that determine testosterone catabolism such as CYP3A4 have been associated with prostate cancer (PCa) risk." (PMID 24924803, 2014). "Two studies have shown that CYP3A4 polymorphisms to confer an increased risk of prostate cancer in men with benign prostatic hyperplasia." (PMID 24282788, 2013). "Polymorphic variations in androgen-regulatory genes may contribute to an increased susceptibility, and recent GWAS studies confirm correlations of biosynthesis and metabolic pathway variants, such as CYP17A1 and CYP3A4, with prostate cancer risk." (PMID 41514571, 2025). "This study indicated G allele and G/G genotype polymorphism in the CYP3A4 gene might be associated with an increased risk of cancers, particularly prostate cancer in African population." (PMID 40630116, 2025).
prostate carcinoma (continued). "Despite these limitations, our meta-analysis suggests that among all studied CYP3A4 variants, CYP3A4*1B might play a role in susceptibility to prostate cancer in European Caucasians." (PMID 41514571, 2025). "These additions strengthen the overall evidence that the CYP3A4*1B variant may modestly influence prostate cancer susceptibility in European Caucasians, although further large-scale studies are needed to confirm this effect." (PMID 41514571, 2025). "The present meta-analysis was intentionally restricted to European Caucasian populations to minimize population stratification and genetic heterogeneity, which could otherwise confound the association between CYP3A4 polymorphisms and prostate cancer risk." (PMID 41514571, 2025). "While some studies have reported associations between the CYP3A4*1B allele and higher clinical grade of PCa, others have failed to observe an association between the presence of the CYP3A4*1B polymorphism and prostate cancer susceptibility." (PMID 24924803, 2014). "In the present case-control study, we investigated whether CYP3A4*1B variant was associated with several clinic characteristics of prostate cancer." (PMID 24924803, 2014). "The CYP3A4 rs2740574 polymorphism was associated with prostate cancer risk and tumor aggressiveness in South African men, after correction for population stratification, and the SRD5A2 rs523349 CG genotype was inversely associated with high-stage disease in Senegalese men." (PMID 23091730, 2012). "This meta-analysis included 6232 allele records of prostate cancer cases and, respectively, 6015 controls from 10 original published studies that explored the association between a potentially functional polymorphism of CYP3A4 and the susceptibility to the disease." (PMID 41514571, 2025). "Androgen receptor-regulated signaling pathways play a key role in the progression of the prostate cancer in which androgen-metabolizing enzymes CYP3A4, CYP3A5, and CYP3A43 are expressed." (PMID 36359206, 2022). "Prostate cells also express CYP3A4 that can inactivate T by conversion to mainly 6βOH-T (with 2β-, 15α/β- and 11β-hydroxyl side product formation) and a decrease of CYP3A4 expression is observed in prostate cancer." (PMID 28865807, 2018). "Most epidemiologic studies of prostate cancer have focused on the genes involved in the steroidogenic pathway, such as P450 cytochrome 3A4 (CYP3A4), CYP17, and SRD5A2." (PMID 24106614, 2013). "Docetaxel clearance in prostate cancer patients has been reported as castration-dependent, with castrated men experiencing a 100% increase in clearance and a two-fold reduction in area under the curve, despite unchanged hepatic CYP3A4 activity." (PMID 40542015, 2025). "Expression of PXR has been found in human prostate tumor tissues, and treatment of PC-3 cells with SR12813 (a selective agonist of PXR) stimulates the expression of multidrug resistance 1 (MDR1) and CYP3A4 and enhances the resistance of these prostate cancer cells to chemotherapy." (PMID 36359206, 2022). "Other CYPs such as CYP3A4 have been examined in prostate cancer." (PMID 37435458, 2022). "On the contrary, in prostate cancer, CYP3A4 is underexpressed." (PMID 36359206, 2022). "A hypothesis is supported by the association between CYP3A4 and CYP3A5 polymorphisms and haplotypes and prostate cancer risk and aggressiveness." (PMID 31309254, 2019). "The CYP3A4*1B/*1B genotype was only present in prostate cancer patients." (PMID 24924803, 2014). "In addition, it is suggested that ritonavir may increase the antitumor activity of docetaxel by inhibition of the CYP3A4‐mediated metabolism of the drug within prostate cancer cells." (PMID 33709626, 2021). "The androgen metabolism genes CYP3A4 and CYP3A5, which encode proteins belonging to the cytochrome P450 (CYP) family of enzymes that are involved in the metabolism of xenobiotics, steroids, vitamins, and sex hormones, have been implicated in prostate cancer risk." (PMID 23091730, 2012).
prostate carcinoma (continued). "The biological assessment included CYP17A1 hydroxylase and lyase inhibition, CYP3A4 and P450 oxidoreductase (POR) inhibition, as well as antiproliferative activity in PC3 prostate cancer cells." (PMID 35204665, 2022). "In addition, the CYP3A4 participates in the process of metabolism and the development of resistance, while indinavir as a potent inhibitor of CYP3A4 is thought to enhance the therapeutic effects of anticancer drugs in androgen-independent prostate cancer cells." (PMID 33986671, 2021). "On the other hand, it has been shown that prostate tissue from prostate cancer patients express lower levels of PXR and CYP3A4 proteins compared to benign prostate tissue from control group." (PMID 24924803, 2014). "More recently, we have shown that RTV blocked docetaxel-induced expression of cytochrome P450 3A4 (CYP3A4) and enhanced antitumour effects of docetaxel against DU145 human prostate cancer cells in vitro and in vivo." (PMID 17133272, 2006). "Despite a higher docetaxel clearance, a similar CYP3A4 activity was observed in castrated vs noncastrated prostate cancer patients." (PMID 33709626, 2021). "In other hormone-dependent neoplasms such as prostate cancer, Chen and colleagues found that PXR activation by the selective potent agonist SR12813 enhanced resistance to chemotherapeutic drugs taxol and vinblastine via PXR-mediated upregulation of CYP3A4 and MDR1 in human prostate cancer PC3 cells." (PMID 24690092, 2014). "TERE1 activation of CYP3A4 is consistent with reports of SXR-induced CYP3A4, which hydroxylates testosterone and progesterone leading to inactive metabolites and resulted in inhibition of androgen-dependent growth of human LAPC-4 prostate cancer cells." (PMID 23919967, 2013). "In the human prostate cancer PC-3 spheroid model that expressed KCa1.1 at a low level (less than 0.001 a.u.), the PAX treatment did not affect the expression level of CYP3A4 transcripts (n = 4 for each, p > 0.05)." (PMID 37958656, 2023).
Obesity (38 papers, 2013 to 2026). Accumulation of substantial excess body fat. "NSAH is itself a risk factor for liver dysfunction, and further study is needed to investigate the relationship of obesity-associated factors such as CYP3A4 or NAFLD/NASH with hepatotoxicity." (PMID 36451213, 2022). "Still, moderate/high risk obesity was significantly more frequent in low CYP3A4 expressers than in normal expressers (13.6% of CYP3A4 low expressers, 1.5% of CYP3A4 normal/high expressers, OR = 13.5 (95% CI 1.2–147.9), p = 0.045)." (PMID 35745668, 2022). "A trend toward lower CYP3A4 activity associated with obesity was also indicated for other major CYP3A4-cleared drugs." (PMID 36199859, 2022). "Although the direct relationship between CYP3A43 and diabetes/obesity was not well known, some variants located in CYP3A4 have been identified in previous studies to be associated with relevant metabolism traits." (PMID 34863089, 2021). "Moderate/high risk obesity (BMI ≥ 35) more frequently occurred in low CYP3A4 expresser patients than in normal/high expressers." (PMID 33277605, 2020). "This study highlights the utility of 4β-OHC/C for continuous monitoring of CYP3A4 activity and possibility to use biomarker-informed VT-PBPK models for individual dose requirements of intravenously administered CYP3A substrates in individuals with obesity over the course of weight loss treatment." (PMID 42317011, 2026). "The CYP3A4*1B SNP has been associated with an increased risk of obesity." (PMID 39523378, 2024). "However, moderate/high risk obesity was significantly more frequent in low CYP3A4 expressers than in normal expressers (13.6% of CYP3A4 low expressers, 1.5% of CYP3A4 normal/high expressers, OR = 13.5 [95%CL = 1.2–147.9], Wald ChiSq = 4.1, N = 87, P = 0.045)." (PMID 33277605, 2020). "Furthermore, moderate/high risk obesity (BMI > 35) frequently occurred in patients expressing CYP3A4 at low level." (PMID 33277605, 2020). "This study evaluated CYP3A4 activity longitudinally in individuals while their obesity status was changing." (PMID 42317011, 2026). "In the future, the relationship between CYP3A4 gene SNPs and its interaction with obesity should be verified in different populations, and more environmental factors should be included in the interaction analysis." (PMID 41242742, 2025). "While clearance of CYP3A4 substrates is lower in patients with obesity, drugs primarily metabolized by UGT, xanthine oxidase, N-acetyltransferase, or CYP2E1 exhibit higher clearance in individuals with obesity." (PMID 40359692, 2025). "Many clinical and experimental studies consistently reported lower hepatic expression and activity of CYP3A4 in obesity and NAFLD." (PMID 36713231, 2023). "In order to minimize the risk of dangerous drug-drug interactions, a washout period of approximately 1–2 weeks should be required for patients with obesity who have stopped taking posaconazole and will be administered a CYP3A4 substrate drug." (PMID 37980304, 2023). "In the present study, growth-related genes, GAL, CENPF, and GPC2, obesity-related gene, PEMT, and CYP3A4, P450, TMEM200B genes were found to be associated with BWF." (PMID 35795788, 2022). "For example, a pediatric study of the CYP3A4 substrate midazolam reported a 38% increase in absolute clearance with obesity, possibly conflicting with adult reports due to lower comorbidity rates in pediatric obesity." (PMID 35359853, 2022). "Several studies have documented reduced CYP3A4 activity in patients with obesity and NAFLD, albeit, the clinical relevance of these findings is not known." (PMID 34598315, 2022). "This also contrasts with midazolam studies in adults with obesity, which suggest a decrease in CYP3A4 metabolism." (PMID 35359853, 2022). "Currently, the question about the required dose adjustment of CYP3A4 substrates in individuals with obesity following BS remains unanswered." (PMID 34598315, 2022).
Obesity (continued). "This supports that patients with obesity have a lower CYP3A4 activity compared with normal weight individuals." (PMID 35648149, 2022). "The effect of CYP1A2 and CYP3A4 expressions on development of obesity was investigated in two separate logistic regression models (for the two levels of obesity) with clozapine dose and treatment duration as covariates." (PMID 33277605, 2020). "Additionally, recent studies have shown in vitro that CYP3A4 is affected by BMI, significantly decreasing its function in patients with severe obesity, restoring its function 6 months after surgery, probably because of an upward adjustment of liver metabolism." (PMID 40610843, 2025). "In this study, we first investigated the impact of CYP3A4 gene-obesity interaction." (PMID 41242742, 2025). "Since obesity reduces the activity of CYP3A4, we could expect higher serum concentrations in patients with obesity." (PMID 38347465, 2024). "Furthermore, the serum albumin and the expression of CYP3A4 decrease with obesity, whereas the expression of UGT1A1 increases." (PMID 38309958, 2024). "Enhanced gut permeability and possible decrease in gut CYP3A4 activity is seen in obesity." (PMID 38347465, 2024). "Since obesity reduces the activity of CYP3A4, we could expect higher serum concentration in patients with obesity." (PMID 38347465, 2024). "Similarly, patients with obesity who were taking a reduced dose of the CYP3A4 substrate drug concomitantly with posaconazole should also observe the same washout period before resuming the recommended monotherapy maintenance dose." (PMID 37980304, 2023). "Conditions such as obesity and non-alcoholic fatty liver disease (NAFLD) are associated with a lower expression and activity of CYP3A4, and several studies suggest that body weight is inversely associated with CYP3A4 activity." (PMID 35648149, 2022). "Even though systemic clearance of midazolam currently is the preferred method for CYP3A4 phenotyping, it may have some important limitations in special populations, e.g., patients with obesity, as shown in the present study." (PMID 35648149, 2022). "Indeed, in obesity, CYP3A4-mediated drug elimination was found to be consistently lower among obese as compared with non-obese subjects." (PMID 33143088, 2020). "Hence, lower CYP3A4 activity in obesity and NAFLD might reduce the generation of NAPQI after an APAP overdose." (PMID 36713231, 2023). "Indeed, CYP3A4 content could be influenced by diseases such as obesity, cancer, infection, and inflammation as the CYP3A4 expression strongly depends on the pregnane X receptor (PXR)." (PMID 35629095, 2022). "We have previously hypothesized that hepatic blood flow may have a more pronounced impact on systemic midazolam clearance than CYP3A4 activity in patients with obesity due to higher liver blood flow in this patient population compared with normal-weight individuals." (PMID 35648149, 2022). "Also, the influence of covariates was evaluated (age, weight, body mass index (BMI), obesity defined as BMI ≥ 30 kg/m2, sex, diabetes mellitus, co-administration of PPI or statins, presence of CYP2C19*2, CYP2C19*17, CYP3A4*1G alleles, and ABCB1 3435 TT genotype)." (PMID 28914344, 2017). "Amitriptyline is primarily metabolized to nortriptyline by CYP3A4 and CYP2C19, both of which have reduced activity in obesity." (PMID 38347465, 2024). "However, as obesity is a major driver of the MetS and both CYP3A4 activity and circulating 4βHC are known to be repressed by obesity and MetS, the repression of hepatic CYP3A4–circulating 4βHC–peripheral LXR pathway could link obesity and disrupted HDL-C metabolism in the obese patients with MetS." (PMID 33182477, 2020). "In fact, the influence of obesity on CYP450 appears to be isoenzyme specific, with a decrease of CYP3A4 activity and an increase of CYP2E1." (PMID 25027286, 2014). "Patients with obesity have been shown to have altered enzyme activity with a negative correlation between BMI and CYP3A4 activity." (PMID 38822847, 2024).